POSTN (periostin)
Diseases named in the same sentence as POSTN in open-access papers (continued):
Sharing a sentence is not in itself a finding about the gene and the disease.
myocardial infarction (59 papers, 2010 to 2025). Gross necrosis of the myocardium, as a result of interruption of the blood supply to the area, as in coronary thrombosis. "In contrast, periostin deficiencies inhibited myocardial regeneration after myocardial infarction in neonatal mice." (PMID 39548113, 2024). "Pressure overload and myocardial infarction are associated with markedly increased POSTN expression in animal models and POSTN has been proposed as an emerging therapeutic target to halt or reduce subsequent cardiac fibrosis." (PMID 37939043, 2023). "This study investigated the association of serum periostin level with cardiac function, coronary situation, biomarkers and clinical characteristics in acute myocardial infarction patients." (PMID 24586384, 2014). "This study was designed to investigate the association of serum periostin level with cardiac function and short term disease prognosis in acute myocardial infarction patients." (PMID 24586384, 2014). "POSTN is also named periostin, and encodes a secreted extracellular matrix protein, playing a significant role in tissue development and regeneration, including wound healing, and ventricular remodeling post myocardial infarction." (PMID 36725968, 2023). "Periostin plays an important role during cardiac development and in the epithelial-mesenchymal transition, and it is also closely associated with cardiovascular diseases such as dilated cardiomyopathy and myocardial infarction (MI)." (PMID 29872491, 2018). "Previous research has demonstrated that POSTN is upregulated in response to myocardial infarction and contributes to the fibrotic remodeling of the heart, a key pathological feature of CAD." (PMID 41409744, 2025). "Elevated levels of periostin have been detected in the serum of patients with acute myocardial infarction, suggesting its potential as a biomarker for cardiac injury." (PMID 41409744, 2025). "It has been shown in fibroblasts that the heparin-binding site at the C-terminus of Periostin can be proteolytically cleaved after myocardial infarction." (PMID 39940700, 2025). "Periostin has also been shown to promote tissue remodeling and cardiac regeneration following myocardial infarction." (PMID 39519329, 2024). "Periostin also plays an important role in early repair through involvement in migration and differentiation of fibroblasts after acute myocardial infarction." (PMID 38435089, 2024). "In a mouse model of myocardial infarction, injected cardiac resident stem cells promoted myocardial regeneration by regulating the M2-type polarization of macrophages through periostin." (PMID 37047322, 2023). "Deletion of periostin-positive myofibroblasts reduces is capable of reducing collagen production and scar formation after myocardial infarction, indicating that periostin-expressing cell type is necessary for and fibrosis in the heart." (PMID 37993768, 2023). "Among these, we next validated by ELISA, and compared with those of naturally‐aged mice, the plasma levels of POSTN (periostin), a secreted matricellular cytokine upregulated in the heart following acute myocardial infarction." (PMID 37565451, 2023). "Periostin expression in cardiac tissue is strongly upregulated in various animal models of cardiac fibrosis and after myocardial infarction and in heart failure." (PMID 36369212, 2022). "In the adult heart, periostin is almost undetectable, but is induced in the ventricles following myocardial infarction, pressure overload, or generalized cardiomyopathy." (PMID 36139018, 2022). "In the heart, periostin expression correlated with myocardial healing in the post-myocardial infarction period and periostin-null mice exhibited a lower degree of local fibrosis and hypertrophy." (PMID 36551967, 2022). "POSTN (periostin) is one of the VK-dependent proteins, which is majorly involved in hematopoiesis, myocardial infarction, fibrosis and bone health." (PMID 36360315, 2022).
myocardial infarction (continued). "Ling revealed that high serum periostin not only correlated with left ventricular ejection fraction but was also a marker of poor prognosis in patients with acute myocardial infarction (AMI)." (PMID 34063373, 2021). "Periostin was found to be involved in tissue repair after vascular injury, e.g., in acute rheumatic fever, hypertensive nephropathy, myocardial infarction, and subarachnoid hemorrhage." (PMID 34063373, 2021). "While periostin has been isolated as an osteoblast-specific molecule, subsequent studies have revealed its expression in cancer tissues, interstitial space during myocardial infarction, and skeletal muscle during muscle regeneration." (PMID 33807264, 2021). "On the other hand, a recent interventional study in rats after myocardial infarction showed a beneficial effect of periostin supply on HDL-cholesterol." (PMID 34063373, 2021). "As periostin delivery promotes myocyte proliferation and reduces injury size and fibrosis in myocardial infarction model rats, IL-13 presumably facilitates STAT3 and periostin induction for heart regeneration." (PMID 32178385, 2020). "When the myocardium is damaged or the heart is remodeled, the expression of periostin is rapidly increased to help the heart heal, inducing the proliferation of differentiated cardiomyocytes, thereby accelerating the repair process of myocardial infarction." (PMID 33241962, 2020). ", and negatively correlated with left ventricular ejection fraction and left atrium diameter, suggesting that serum periostin levels can be used as a predictor of short-term poor prognosis in AMI patients(all types of myocardial infarction patients)." (PMID 33241962, 2020). "Genetic loss of periostin function from activated fibroblasts attenuates fibrotic remodeling in response to LV pressure overload, and delivery of a periostin neutralizing antibody improves post-myocardial infarction remodeling." (PMID 31374110, 2019). "Lineage tracing studies revealed that periostin-expressing myofibroblasts play a pivotal role during healing and fibrosis in the heart following myocardial infarction." (PMID 31417912, 2019). "Periostin stimulates healing after myocardial infarction in mice through induction of cardiomyocyte proliferation, and it is known to be responsible of collagen cross-linking (covalent linkage of collagen fibers)." (PMID 31221719, 2019). "In the adult heart periostin is induced following myocardial infarction, pressure overload, or generalized cardiomyopathy." (PMID 29695980, 2018). "Periostin has been reported to be induced in response to myocardial infarction and during diabetic cardiomyopathy and to play an important signaling role in driving cardiac fibrosis." (PMID 30356742, 2018). "It has been suggested that recombinant periostin had regenerative properties and can induce cardiomyocyte proliferation after myocardial infarction, but these results have been contested by other investigators." (PMID 29695980, 2018). "For instance circulating periostin levels are decreased after myocardial infarction, but are increased in patients with dilated cardiomyopathy." (PMID 29695980, 2018). "Pathological stress, such as pressure overload or myocardial infarction, increases cardiac periostin expression." (PMID 28767701, 2017). "Periostin, a matricellular protein, plays a critical role in regulating fibrogenesis of various diseases, such as heart failure, myocardial infarction and idiopathic pulmonary fibrosis." (PMID 26750922, 2016). "In vivo, valsartan can also significantly attenuate the increased periostin expression, accompanied by improvement of cardiac dysfunction in acute myocardial infarction rat models." (PMID 26281830, 2015). "Periostin was proved to play an important role in extra-cellular matrix remodeling after acute myocardial infarction (AMI)." (PMID 24586384, 2014).
myocardial infarction (continued). "The aim of this study was to develop a safe method for delivering regeneration factors to the heart and to test the functional and structural effects of periostin peptide treatment in a large animal model of myocardial infarction (MI)." (PMID 23700403, 2013). "For example, the significance of a recent high-profile study on periostin as a potential therapeutic target after heart attack has been questioned on the basis of this work being partly based on a version of periostin lacking the C-terminal region." (PMID 20109226, 2010). "In pathological heart conditions, periostin expression has been described both in the context of acute events (myocardial infarction), as well as chronic pathological conditions (pressure overload)." (PMID 20109226, 2010). "Interestingly, serum periostin has also been found to be increased in patients following myocardial infarction, and it predicted adverse cardiac remodeling months later." (PMID 40743121, 2025). "Accumulating evidence underpins the putative role of periostin in the development of several cardiovascular diseases, including cardiac fibrosis, atrial fibrillation, aortic dissection, acute myocardial infarction, arterial calcification, atherosclerosis, and pulmonary arterial hypertension." (PMID 37993768, 2023). "In a study focused specifically on the role of active fibroblasts in myocardial infarction in mice, a subpopulation called cells reparative cardiac fibroblasts (CFRs), was identified by the expression of POSTN and collagen triple helix repeat containing 1 (CTHRC1)." (PMID 35548426, 2022). "Analysis of periostin isoforms revealed that the expression patterns of each isoform differed between intact and regenerating muscle; additionally, these patterns showed similar changes in cardiac muscle during acute myocardial infarction." (PMID 33807264, 2021). "In addition, the expression of periostin will also be significantly increased in pathological processes such as tumors, myocardial infarction, and wound repair." (PMID 33241962, 2020). "Moreover, it has been reported that periostin induces cell cycle reentry in cardiomyocytes, followed by improving ventricular remodeling and cardiac function after myocardial infarction, although these effects are still controversial." (PMID 32000779, 2020). "In addition, the survival rate of myocardial infarction decreases with the reduction of periostin-expressing myofibroblasts, suggesting that fibrosis is an effective mechanism for repairing myocardium." (PMID 32582717, 2020). "Consistent with increased fibrosis, they exhibited increased abundance of periostin, a transforming growth factor β-inducible matricellular protein known to play an important role in cardiac fibrosis and induced post-myocardial infarction and in diabetic cardiomyopathy." (PMID 30356742, 2018). "In the heart, periostin production by fibroblasts was demonstrated to be crucial for collagen fibrilogenesis and cardiac healing short-term after myocardial infarction, whereas in chronic cardiac disease models periostin null mice were protected from hypertrophy and fibrosis." (PMID 28536691, 2017). "Periostin is integral to wound healing, skin sclerosis, and fibrosis in myocardial infarction." (PMID 26895702, 2016). "However, after cardiac injury such as myocardial infarction, pump failure or pressure overload, the mRNA and protein expression of periostin were greatly elevated in the heart." (PMID 24586384, 2014). "Furthermore, inducible periostin overexpression protected mice from rupture following myocardial infarction but induced spontaneous hypertrophy with aging." (PMID 24146092, 2014). "Our study found that serum periostin was in negative association with left ventricular ejection fraction and left atrium diameter as well as in positive association with Killip class in acute myocardial infarction patients." (PMID 24586384, 2014).
myocardial infarction (continued). "However, the complex of periostin, miR-203-3p, and small nucleolar RNA host gene 8 (Snhg8) mediated neonatal mouse cardiomyocytes (NMCMs) apoptosis after hypoxia-treated NMCMs, contributing to acute myocardial infarction." (PMID 36611844, 2022). "In this study, we examined whether gene expressions are modulated by ACEI (temocapril), ARB (olmesartan) or both in a murine model with transverse aortic constriction (TAC) and confirm whether periostin is a target gene of olmesartan in mice with myocardial infarction (MI)." (PMID 29872491, 2018). "Periostin may play a role in fibrosis and tissue remodeling following myocardial infarction." (PMID 29872491, 2018). "Periostin is a matricellular protein that is reactivated during tissue damage and repair and has been shown to be a critical regulator of multiple biological pathways involved in the repair of tissue after myocardial infarction, peripheral vascular disease, and skin wounds." (PMID 26537950, 2015). "Furthermore we quantified the density of capillaries in the peri-infarcted region to determine whether periostin stimulates angiogenesis after myocardial infarction." (PMID 23700403, 2013). "Periostin is a regulator of fibrosis and collagen deposits, and although it has been recognized for the important role it plays in myocardial repair/remodeling following myocardial infarction, there are indicators that its overexpression in the nasal mucosa contributes to tissue repair and fibrosis." (PMID 23533421, 2013). "Administration of a recombinant peptide of Periostin (rPN) has recently been shown to stimulate cardiomyocyte proliferation and angiogensis after myocardial infarction (MI)." (PMID 22590609, 2012). "Another study showed that compared with the control group, knockdown of POSTN in AMI mice models significantly increased fibrosis and cardiomyocyte regeneration after myocardial infarction." (PMID 37572219, 2023). "However, once fibroblasts become activated or the heart suffers injury (e.g., myocardial infarction), fibroblasts may also strongly express other markers such as periostin (POSTN), alpha smooth muscle actin (αSMA) or mesenchyme homeobox 1 (MEOX1), among other genetic signatures." (PMID 35548426, 2022). "In addition, in cardiology, the expression of periostin is rapidly up-regulated when the myocardium damaged or during cardiac remodeling, which helps the heart to heal and induces the proliferation of differentiated cardiomyocytes, thereby accelerating the repair process of myocardial infarction." (PMID 33241962, 2020). "Periostin, a secreted extracellular matrix (ECM) protein, is upregulated dramatically under transverse aortic constriction (TAC) stress, myocardial infarction or heart failure." (PMID 26750922, 2016). "We also observed a marked up-regulation of POSTN, a protein involved in proper ECM synthesis and in the hypertrophic response following myocardial infarction." (PMID 21541333, 2011). "Previous studies had found that POSTN was basically not expressed in the normal adult heart tissues, and highly expressed after cardiac injury such as myocardial infarction, pressure overload, and dilated cardiomyopathy." (PMID 37572219, 2023). "In mice with myocardial infarction, TCF21 lineage-traced cells could transform into periostin-expressing myofibroblasts, which is necessary for adaptive healing and fibrosis in the heart." (PMID 32582717, 2020). "The next studied gene is PERIOSTIN (POSTN), whose excessive expression has recently been shown in other types of tissues, including cerebral tissue, sperm or T lymphocytes, and myocardium, taking part in the remodelling following a myocardial infarction." (PMID 25573836, 2015). "Although the net effect of periostin on ventricular remodeling after acute myocardial infarction has not reached a consensus, there is no doubt that this molecule acts as an important regulator in this process." (PMID 24586384, 2014).
myocardial infarction (continued). "Acute myocardial infarction patients showed decreased circulating level of periostin compared with control volunteers and periostin level was in negative correlation with patients’ cardiac function three months after AMI." (PMID 24586384, 2014). "In order to verify the potential role of POSTN and its alternative splicing in AMI, we examined the plasma POSTN protein levels of AMI patients at different stages, and also the expression level of POSTN gene in peripheral blood mononuclear cell (PBMC) within 24 h of myocardial infarction." (PMID 37572219, 2023). "Thus, TGFBI and periostin act similarly in the heart in affecting fibrosis and disease responsiveness, although TGFBI is not seemingly necessary in the heart after myocardial infarction injury and is fully compensated by the more prominently expressed effector periostin." (PMID 28750100, 2017).